MARCHF2 (membrane associated ring-CH-type finger 2)
Description:
E3 ubiquitin-protein ligase that may mediate ubiquitination of TFRC and CD86, and promote their subsequent endocytosis and sorting to lysosomes via multivesicular bodies. E3 ubiquitin ligases accept ubiquitin from an E2 ubiquitin-conjugating enzyme in the form of a thioester and then directly transfer the ubiquitin to targeted substrates. Together with GOPC/CAL mediates the ubiquitination and lysosomal degradation of CFTR. Ubiquitinates and therefore mediates the degradation of DLG1. Regulates the intracellular trafficking and secretion of alpha1-antitrypsin/SERPINA1 and HP/haptoglobin via ubiquitination and degradation of the cargo receptor ERGIC3. Negatively regulates the antiviral and antibacterial immune response by repression of the NF-kB and type 1 IFN signaling pathways, via MARCHF2-mediated K48-linked polyubiquitination of IKBKG/NEMO, resulting in its proteasomal degradation. May be involved in endosomal trafficking through interaction with STX6. (Microbial infection) Positively regulates the degradation of Vesicular stomatitis virus (VSV) G protein via the lysosomal degradation pathway. Represses HIV-1 viral production and may inhibit the translocation of HIV-1 env to the cell surface, resulting in decreased viral cell-cell transmission.
Synonyms: MARCH-II; MARCH2; RNF172; HSPC240
Tractability: Antibody: UniProt places it where antibodies can reach, with high confidence; its Gene Ontology location is reachable by antibodies, with high confidence; UniProt predicts a signal peptide or a membrane-spanning region.
Gene: Protein-coding gene on chromosome 19 (8,411,460 to 8,439,017, forward strand). Ensembl gene ENSG00000099785.
Subcellular location: Endoplasmic reticulum membrane; Lysosome membrane; Endosome membrane; Golgi apparatus membrane; Cytoplasm; Cell membrane
Subcellular location (Human Protein Atlas): Endoplasmic reticulum; Cytosol
Gene Ontology:
Molecular function: protein binding; ubiquitin protein ligase activity; ubiquitin-protein transferase activity; zinc ion binding
Biological process: positive regulation of lysosomal protein catabolic process; protein ubiquitination; suppression of viral release by host; antibacterial innate immune response; antiviral innate immune response
Cellular component: cytoplasm; cytoplasmic vesicle; endoplasmic reticulum; endoplasmic reticulum membrane; endosome membrane; Golgi membrane; lysosomal membrane; plasma membrane
Genetic constraint (gnomAD): Loss-of-function variants: 22 observed, 25.37 expected, observed/expected ratio (o/e) 0.87, 90% interval 0.62 to 1.24. The upper end of that interval is the gene's LOEUF score, 1.24, which puts it in group 5 of 6, group 1 being the genes least tolerant of losing a copy. Missense variants: 301 observed, 342.72 expected, observed/expected ratio (o/e) 0.88, 90% interval 0.8 to 0.97. Synonymous variants: 154 observed, 156.33 expected, observed/expected ratio (o/e) 0.99, 90% interval 0.86 to 1.13.
Homologues: Orthologues: macaque MARCHF2 (99% identical), mouse Marchf2 (95% identical), guinea pig MARCHF2 (94% identical), rabbit MARCHF2 (94% identical), pig MARCHF2 (93% identical), chimpanzee MARCHF2 (80% identical), rat Marchf2 (80% identical), dog MARCHF2 (78% identical), tropical clawed frog marchf2 (78% identical), zebrafish marchf2 (78% identical). Paralogues in human: MARCHF3 (66% identical), MARCHF1 (25% identical), MARCHF4 (24% identical), MARCHF8 (24% identical), MARCHF9 (23% identical), MARCHF11 (21% identical).
Diseases named in the same sentence as MARCHF2 in open-access papers:
MARCHF2 is named in the same sentence as 26 diseases in open-access papers, as found by Europe PMC text mining. Sharing a sentence is not in itself a finding about the gene and the disease. The quoted sentences say what the papers report.
triple-negative breast carcinoma (3 papers, 2025). An invasive breast carcinoma which is negative for expression of estrogen receptor (ER), progesterone receptor (PR), and human epidermal growth factor receptor 2 (HER2). "Conversely, in triple-negative breast cancer (TNBC), the E3 ligase Membrane Associated Ring-CH-Type Finger 2 (MARCH2) ubiquitinates Snail, driving its degradation and suppressing tumor growth and metastasis." (PMID 41208892, 2025).
MARCHF2 also shares sentences with these, for which no sentence is quoted: HIV-1 infection (6 papers); infection (5); tumor (5); viral infections (5); colon carcinoma (3); bacterial infection (2); breast carcinoma (2); cancer (2); pancreatic cancer (2); cardiovascular diseases (1); clear cell renal cell carcinoma (1); colorectal cancer (1); dentin caries (1); dilated cardiomyopathy (1); hepatocellular carcinoma (1); hypertrophic cardiomyopathy (1); ischemic cardiomyopathy (1); kidney tumors (1); lung adenocarcinoma (1); lung squamous cell carcinoma (1); metastatic tumors (1); myocardial infarction (1); ovarian carcinoma (1); stomach cancers (1); Type 2 Diabetes (1).